DUSP1 (dual specificity phosphatase 1)
Diseases named in the same sentence as DUSP1 in open-access papers (continued):
Sharing a sentence is not in itself a finding about the gene and the disease.
viral infection (8 papers, 2010 to 2024). "DUSPs, specifically DUSP1, have been implicated in other viral infections as well, including hepatitis C virus (HCV), vaccinia virus (VACV), human respiratory syncytial virus (RSV), and Sendai virus (SeV)." (PMID 34578413, 2021). "Our results showed the upregulation of the DUSP1 transcript during bacterial and viral infections, which was reversed by m6A- and YTHDF2-mediated transcript degradation." (PMID 36625590, 2023). "Our results showed that the DUSP1 transcript was indeed induced during bacterial and viral infections, together with the activation of the ERK, JNK, and p38 MAPK pathways." (PMID 36625590, 2023). "In conclusion, bacterial and viral infections activate MAPKs to induce innate immune response genes as well as a negative regulator of MAPKs, DUSP1, to avoid an excessive innate immune response." (PMID 36625590, 2023). "Western blot results showed that the levels of phosphorylated p38 (p-p38) and p-JNK were increased following DUSP1 knockdown during bacterial and viral infections." (PMID 36625590, 2023). "From these findings, we conclude that activation of MAPKs by virus infection contributes to the replication of MVA in DUSP1 KO cells." (PMID 24244156, 2013). "Although several reports have highlighted the importance of DUSP1 in parasite and bacterial diseases, there is limited information on the involvement of DUSP1 in viral infections." (PMID 24244156, 2013). "At present, little is known about the role of DUSP1 in host immune responses during viral infections." (PMID 24244156, 2013). "To determine whether DUSP1 regulated the activation of MAPKs during bacterial and viral infections, we performed DUSP1 knockdown." (PMID 36625590, 2023). "These previous findings provide the premise to hypothesize that when DUSP1 is knocked down during JCPyV infection in NHAs, viral infection is reduced because STAT1 is translocated to the nucleus, activating ISGs and thus inhibiting JCPyV infection." (PMID 34578413, 2021). "Even when ERK1/2 is phosphorylated upon DUSP1 reduction, the host response to viral infection may overcome the additional activation of ERK1/2." (PMID 34578413, 2021). "At present, little is known about the role of DUSP1 in viral infections." (PMID 24244156, 2013). "However, little information has been reported regarding the involvement of DUSP1 in viral infections." (PMID 24244156, 2013). "Nevertheless, little is known about the function of DUSP1 in viral infections." (PMID 24244156, 2013). "Altered activation of MAPKs during viral infection in the absence of DUSP1 might be the cause of the differences observed in VACV host range and replication." (PMID 24244156, 2013). "In this study, we have discovered that DUSP1 is a direct m6A target, and m6A and the reader protein YTHDF2 regulate DUSP1 stability to maximize the innate immune response during bacterial and viral infections." (PMID 36625590, 2023). "Since DUSP1 inactivated p38 and JNK during bacterial and viral infections, and ALKBH5 knockdown reduced DUSP1 transcript stability by increasing the m6A level, we examined ALKBH5’s regulation of p38 and JNK activation." (PMID 36625590, 2023). "Altogether, research has demonstrated the role of DUSP1 in the MAPK/ERK pathway and the influence it has on alternative pathways can either enhance or reduce viral infection." (PMID 34578413, 2021). "In fact, DUSP1 is under the tight control of m6A and YTHDF2 during bacterial and viral infections." (PMID 36625590, 2023). "Indeed, the knockdown of DUSP1 or the m6A eraser ALKBH5 enhanced the expression of innate immune response genes, including IL-1β, CSF3, TGM2, and SRC, during bacterial or viral infections." (PMID 36625590, 2023). "DUSP1 regulates p38 and JNK phosphorylation during bacterial and viral infections." (PMID 36625590, 2023). "The role of DUSP1 in the innate response to virus infection is far less known and, to our knowledge, was not previously assessed in the context of infection by RSV or SeV." (PMID 29234123, 2017).
viral infection (continued). "More interestingly, host restriction of MVA replication in murine cells is overcome when DUSP1 is absent and activation of MAPKs by virus infection contributes to this enhanced replication." (PMID 24244156, 2013). "DUSP1, with its multiple roles in modulating the MAPK cascade and response to steroid hormones, points to its involvement in signaling pathways that regulate inflammation and immune responses, potentially influencing the host’s defensive mechanisms against the viral infection." (PMID 39456924, 2024). "This indicates that DUSP1 is dispensable during JCPyV infection in cells immortalized with SV40 T Ag, as reduction of this phosphatase did not alter viral infection." (PMID 34578413, 2021).
Alzheimer disease (7 papers, 2019 to 2024). A progressive, neurodegenerative disease characterized by loss of function and death of nerve cells in several areas of the brain leading to loss of cognitive function such as memory and language. "Concerning the relevant role of DUSP1 in the regulation of synaptic plasticity and neuronal morphology, impaired physiology of DUSP1 is also evident in Alzheimer’s disease (AD)." (PMID 31018603, 2019). "In addition, DUSP1 is a hub-gene shared of OSA and Alzheimer Disease (AD) patients, and DUSP1-mediated oxidative stress involved in the pathogenesis of OSA affecting AD." (PMID 38178888, 2023).
autoimmune disease (7 papers, 2019 to 2026). A disorder resulting from loss of function or tissue destruction of an organ or multiple organs, arising from humoral or cellular immune responses of the individual to their own tissue constituents. "STAP1 and DUSP1 are significantly associated with anti-inflammatory responses and immune infiltration in human autoimmune diseases." (PMID 35581549, 2022). "Additionally, DUSP1 has been associated with the development of several autoimmune diseases." (PMID 39697434, 2024). "Conversely, decreased Dusp1 expression can result in excessive Erk1/2 activation, contributing to inflammatory responses and autoimmune diseases." (PMID 39472573, 2024). "Besides autoimmune diseases, reduction of DUSP1, DUSP2, and DUSP14, as well as induction of DUSP8 contribute to the pathogenesis of allergic diseases." (PMID 42087139, 2026). "Moreover, the inhibition of DUSP1 expression or function in T cells may be beneficial for the treatment of T cell-mediated autoimmune diseases such as multiple sclerosis." (PMID 36250071, 2022). "Downregulation of DUSP1, DUSP3, DUSP11, and DUSP22, as well as upregulation of DUSP4, DUSP6, and DUSP23 are involved in human autoimmune diseases." (PMID 42087139, 2026). "Nevertheless, the inhibition of DUSP1 and overexpression of DUSP5 may be potential therapeutic approaches for autoimmune diseases, including SLE." (PMID 31766293, 2019). "In addition, DUSPs are also involved in either human autoimmune diseases (DUSP2, DUSP7, DUSP10, and DUSP12) or T-cell activation (DUSP1, DUSP5, and DUSP14)." (PMID 31766293, 2019).
cognitive deficits (7 papers, 2016 to 2025). "Mean levels of DUSP1 protein are reduced only in the category presenting severe cognitive deficits, proportionate to Braak stages." (PMID 27849045, 2016). "RGS1 and DUSP1 showed differential expression across all three cognitive impairments." (PMID 40624693, 2025).
Hepatic steatosis (7 papers, 2018 to 2025). Steatosis is a term used to denote lipid accumulation within hepatocytes. "Experiments in which grossly obese leptin-resistant (db/db) mice were crossed with DUSP1−/− animals revealed that loss of DUSP1/MKP-1 protected against hepatic steatosis." (PMID 30401534, 2019).
Huntington disease (7 papers, 2016 to 2024). Huntington disease (HD) is a rare neurodegenerative disorder of the central nervous system characterized by unwanted choreatic movements, behavioral and psychiatric disturbances and dementia. "Low levels of DUSP1 have been associated with neurological pathologies such as Huntington disease, multiple sclerosis, ischemia or cerebral hypoxia." (PMID 30938680, 2019). "Downregulation in DUSP1 transcripts was also described in the cortex and striatum of mice models of Huntington’s disease (HD) and postmortem samples of HD patients, in addition to decrease in DUSP1 activity in PD patients." (PMID 37971544, 2024). "Previous overexpression of DUSP1 with viral vectors in the striatum of a mouse model of Huntington’s disease provided neuroprotective effects." (PMID 27849045, 2016).
Hyperglycemia (7 papers, 2014 to 2022). An increased concentration of glucose in the blood. "Furthermore, the decreased levels of DUSP1 in the CVD diabetic group might be linked with hyperglycemia in these subjects." (PMID 30647800, 2018). "DUSP1 overexpression suppresses hyperglycemia-induced mitochondrial fission by regulating Mff-related mitochondrial dynamics." (PMID 34067150, 2021). "In addition, downregulated DUSP1 expression induced by hyperglycemia activates JNK pathway, leading to phosphorylated Mff-mediated mitochondrial fission." (PMID 34067150, 2021). "DUSP1 is downregulated in the renal tissue of hyperglycemia-induced diabetic mice." (PMID 34067150, 2021). "However, unlike DUSP1−/− mice MKP-1-LKO animals exhibited increased adiposity, fasting hyperglycaemia and hyperinsulinemia on a normal chow diet, indicating that hepatic DUSP1/MKP-1 regulates glucose homeostasis." (PMID 30401534, 2019).
neuroblastoma (7 papers, 2012 to 2025). Neuroblastoma (NB) is the most common solid, extracranial childhood tumor. "Here, we demonstrated that BCI, an allosteric inhibitor of DUSP1/6 phosphatases, upregulates P2rx7 gene expression in neuroblastoma cells via p38 MAPK, adding to the factors implicated in the control of P2RX7 expression." (PMID 36589747, 2022). "Together, our results indicate that dual specificity phosphatase 1 acts as a novel negative regulator of P2X7 receptor expression in neuroblastoma cells due to the downregulation of the p38 pathway." (PMID 36589747, 2022). "In summary, our data highlight DUSP1 as a novel negative regulator of P2RX7 expression in neuroblastoma cells due to the downregulation of the p38 pathway." (PMID 36589747, 2022). "DUSP1 expression also increases the survival of cortical neurons and neuroblastoma cells when submitted to hypoxia-deoxygenation, while DUSP1 silencing abolishes this protective effect." (PMID 31018603, 2019). "Recently, studies performed with the DUSP1/DUSP6 inhibitor BCI showed that p38 activation also upregulates P2X7R levels in neuroblastoma cells, indicating that the DUSP1 phosphatase may negatively modulate P2X7R expression by dampening the p38 pathway." (PMID 37776398, 2024). "This study examined whether the cytotoxic effects of BCI on neuroblastoma tumour cells were exerted by its known inhibitory action on dual specificity phosphatases DUSP1 and DUSP6." (PMID 35478300, 2022). "Both these studies demonstrated that a 24 h exposure to BCI significantly enhanced the levels of P2RX7, suggesting that a DUSP1/6-dependent mechanism may be involved in the upregulation of this receptor in neuroblastoma cells." (PMID 36589747, 2022). "Significantly, we found that both nuclear DUSP1 and cytosolic DUSP6 phosphatases were expressed strongly in serum deprived N2a neuroblastoma cells." (PMID 36589747, 2022). "MKPs, and particularly DUSP1 and DUSP6, have been proposed as cancer biomarkers, since aberrant expression of these phosphatases has been found in a wide variety of human cancers, including neuroblastoma." (PMID 36589747, 2022). "Previous studies demonstrated that BCI decreased neuroblastoma cell viability in a dose-dependent and time-dependent manner, although its cytotoxicity appears to be at least partially independent of DUSP1/6 activity." (PMID 36589747, 2022). "Enhance P2X7 receptor expression by downregulation of the p38 pathway in neuroblastoma cells, and exert cytotoxicity after deletion of DUSP6 and DUSP1 (CRISPR-Cas9) in neuroblastoma cells, suggesting that BCI cytotoxicity does not depend on DUSP1 or DUSP6 status in neuroblastoma cells." (PMID 41158869, 2025).
oral cancer (7 papers, 2013 to 2025). "The increased polarization of macrophages toward M2 was also found with a DUSP1 deficiency in an oral cancer mice model, implying that DUSP1 deficiency enhances tumor-associated inflammation." (PMID 38139370, 2023). "Prior reports have indicated that DUSP1 regulates oral cancer-associated inflammation and leukocyte infiltration." (PMID 36387242, 2022). "In the future, the effects of increased DUSP1 expression on the growth of oral cancer cells should be investigated." (PMID 40415961, 2025). "At the same time, it is known that the decreased expression of DUSP1 in oral cancer tissue is due to the hypermethylation of its promoter region." (PMID 38139370, 2023). "Therefore, the finding that S. mitis can upregulate DUSP1 in vitro points to a significant potential mechanism for its anti-oncogenic effects; however, direct validation of this specific S. mitis-DUSP1 interaction in an in vivo oral cancer model remains a critical research gap." (PMID 41368437, 2025). "On the other hand, silencing of DUSP1 in HCC and oral cancer activates p38, ERK1/2, and JNK pathways that can modulate polarization of TAMs toward the M2 (anti-inflammatory) phenotype, and isoforms DUSP1, DUSP4, DUSP5, and DUSP6 potentially modulate TAM maturation and polarization." (PMID 41158869, 2025). "However, specific reports regarding the involvement of DUSP1 in the cell cycle of oral cancer cells have not been published." (PMID 40415961, 2025).
osteoarthritis (7 papers, 2015 to 2025). A noninflammatory degenerative joint disease occurring chiefly in older persons, characterized by degeneration of the articular cartilage, hypertrophy of bone at the margins and changes in the synovial membrane. "We also performed KEGG enrichment analysis and PPI protein interaction network analysis, and we found that DUSP1 could be involved in osteoarthritis and showed a close association with MAPK pathway." (PMID 37340458, 2023). "DUSP1 has a protective effect on osteoarthritis by intercepting the expression of MMP-13 and activating the MAPK pathway." (PMID 36681837, 2023). "Four genes, MYC, JUN, DUSP1 and NFKBIA, were selected as potential diagnostic biomarkers in osteoarthritis." (PMID 36681837, 2023). "Consistently, we found that expression of MYC, JUN and DUSP1 was markedly reduced in synovial tissues of osteoarthritis patients than that of normal controls (p value < 0.05)." (PMID 36681837, 2023). "It was shown that DUSP1 can inhibit osteoarthritis by suppressing the activation of the p38 MAPK signaling pathway and exerting anti-inflammatory and anti-catabolic actions." (PMID 37340458, 2023). "Hyaluronic acid, which is injected intra-articularly as a treatment for osteoarthritis, also induces DUSP-1." (PMID 35008797, 2021). "It has been reported that DUSP1 inhibits the activation of the P38 MAPK pathway, thereby slowing the pathogenesis of osteoarthritis." (PMID 37340458, 2023). "Among them, four genes (MYC, JUN, DUSP1 and NFKBIA) specifically expressed in immune system were identified and clinical samples revealed consistent change of these four genes in synovial tissue retrieved from patients with osteoarthritis." (PMID 36681837, 2023). "Finally, four feature genes, including MYC, JUN, DUSP1 and NFKBIA were identified, which had well predictive performance in osteoarthritis." (PMID 36681837, 2023). "MYC, JUN, DUSP1 and NFKBIA might be biomarkers and potential therapeutic targets in osteoarthritis." (PMID 36681837, 2023).
Parkinson disease (7 papers, 2014 to 2024). A progressive degenerative disorder of the central nervous system characterized by loss of dopamine producing neurons in the substantia nigra and the presence of Lewy bodies in the substantia nigra and locus coeruleus. "Furthermore, CP-673451 treatment could also be of great benefit for tackling neurological disorders such as Alzheimer’s, Huntington’s and Parkinson’s diseases, in which DUSP1 dysregulation has been reported." (PMID 35393545, 2022). "Genes in the low-expression cohorts of DUSP1, FOS, and NFIL3 were mainly enriched in oxidative phosphorylation, as well as Parkinson's disease." (PMID 38384585, 2024). "DUSP1 and DUSP6 phosphatases also behave as molecular markers of the progression and prognosis of Parkinson’s disease (PD)." (PMID 31018603, 2019). "Our data show that several pathways related to neurodegenerative diseases (including Huntington’s, Alzheimer’s and Parkinson’s disease) were enriched in the absence of DUSP1." (PMID 34572983, 2021).
Stroke (7 papers, 2018 to 2025). Sudden impairment of blood flow to a part of the brain due to occlusion or rupture of an artery to the brain. "In stroke-related field, evidences on DUSP1 were mostly limited to gene expression for IS diagnosis, which rarely involved a transcriptional regulatory mechanism and immune infiltration." (PMID 35746962, 2022). "The DUSP1 has emerged as an endogenous neuroprotective factor in stroke." (PMID 40823304, 2025). "In endothelial cells, DUSP1 overexpression preserves blood–brain barrier integrity by inactivating MAPK, thereby reducing brain injury and improving post-stroke outcomes." (PMID 40823304, 2025). "In this study, we analyzed the expression of DUSP1, NCOA4 and SLC2A3 at 3, 5 and 24 h after stroke based on the GSE58294 dataset." (PMID 37699956, 2023). "Pharmacological activation of DUSP1, or inhibition of upstream ERK signaling, could theoretically mitigate injury in hyperinflammatory stroke subtypes." (PMID 40636523, 2025). "Multivariate logistic regression analysis revealed that among the molecular variables, DUSP1 (OR = 2.39, 95% CI: 0.87–6.57; p = 0.092) and GADD45B (OR = 2.53, 95% CI: 0.63–10.22; p = 0.192) showed a trend toward stroke association, though neither reached statistical significance." (PMID 40636523, 2025).
cardiomyopathy (6 papers, 2014 to 2025). A disease of the heart muscle or myocardium proper. "Depletions of different DUSPs in mice have shown changes in cardiomyocyte morphology (DUSP8,), or have been linked to protection (DUSP6,) or, in contrast, to increased susceptibility to cardiomyopathy (DUSP1, DUSP4,)." (PMID 36227898, 2022). "The role of DUSP1 in protecting the heart from cardiomyopathy by inhibiting the MAPK effectors was shown in the Dusp1/Dusp4 double-knockout mouse model." (PMID 35625658, 2022). "DUSP1 is cardioprotective genes that play a critical role in the heart by dampening p38 MAPK signaling that would otherwise reduce contractility and induce cardiomyopathy." (PMID 37334672, 2023). "Coming from a fairly large family with 25 members, it is conceivable that different DUSPs may have overlapping functions, a possibility that is supported by a recent report showing that concomitant deletions of DUSP1 and DUSP4 are required for the induction of cardiomyopathy." (PMID 26710253, 2015). "Support for functional redundancy amongst the nuclear DUSPs comes from the recent report showing that in contrast to mice lacking either DUSP1 or DUSP4, which exhibit no cardiac pathology, mice missing both of these DUSPs develop cardiomyopathy due to unrestrained p38 activation." (PMID 25375135, 2014).